KRAS (KRas proto-oncogene, GTPase)
Diseases named in the same sentence as KRAS in open-access papers (continued):
Sharing a sentence is not in itself a finding about the gene and the disease.
cancer (continued). "In vitro drug sensitivity testing using an established SCCC organoid revealed that among the two therapeutic targets of precision medicine identified, the KRAS pathway inhibitor exerted adequate anti‐cancer effects compared to the MYC inhibitor." (PMID 36691316, 2023). "G12 mutations produce significant effects on the conformational states of KRAS and are involved in the development of human cancers." (PMID 37049650, 2023). "RAS genes (KRAS, HRAS and NRAS) comprise the most frequently mutated oncogene family in human cancer." (PMID 37807065, 2023). "The anaplerotic feeding of the glutaminolysis metabolite α-KG into the TCA cycle is essential for the growth of various anchorage-independent, KRAS-induced cancer cells." (PMID 36959802, 2023). "Although the therapeutic potential of inhibiting STK33 in patients with KRAS-mutant cancer is controversial, STK33 remains an attractive therapeutic target in several other cancers." (PMID 38087254, 2023). "The inhibitors covalently targeting oncogenetic mutant KRAS showed rather good anti-cancer activity." (PMID 37110848, 2023). "The aromatic nitrogen (N) of binimetinib forms a stronger hydrogen bond interaction with S212 binding site than aromatic fluorine (F) of cobimetinib, which means binimetinib has a higher potency in KRAS-driven cancers than cobimetinib." (PMID 37808191, 2023). "CMS3 cancers with KRAS mutations presented a slight upregulation of claudin 4, while CMS3 cancers with wild-type KRAS displayed suppressed expression of claudin 4 (two-tailed t test p < 0.05, left)." (PMID 37998722, 2023). "Mutant KRAS drives approximately 25% of all cancers and has traditionally been considered “undruggable”." (PMID 37141389, 2023). "For patients with KRAS WT cancer across all treatment types in the 2L setting, significantly shorter OS was observed in patients with mSTK11-mKEAP1 vs STK11 WT-KEAP1 WT (3.5 vs 8.3 months; aHR, 1.83; 95% CI, 1.35–2.49; p < 0.001)." (PMID 37069542, 2023). "Key genes involved in these pathways including RAS (KRAS, NRAS, HRAS), BRAF, PIK3CA, and MET are often mutated in human cancers, and these mutations have been suggested to promote the Warburg‐effect." (PMID 35785488, 2023). "The two pan-KRASi had a similar binding mode to mutant KRAS as well as similar inhibitory properties in RASless MEFs and cancer cell lines." (PMID 37258666, 2023). "Next, because a recent study showed that amplification is the major activation mechanism of KRASin GAC cancer and that KRAS amplification is significantly associated with resistance to MAPK blockade, we assessed copy number alterations of KRAS by subtype." (PMID 37674200, 2023). "Collectively, these findings nominate JAK2 inhibitors as potential drugs for the treatment of KRAS-driven cancers." (PMID 37210549, 2023). "Nonetheless, the information about PITPNC1 in cancer is far from being completed, furthermore in the context of dominant oncogenes such as KRAS." (PMID 37210549, 2023). "The development of GC is associated with mutations in oncogenes, cancer suppressor genes, and DDR-related genes, such as KRAS and BRCA1/2, which promote genomic instability and carcinogenesis." (PMID 37457685, 2023). "Autophagy is necessary for the maintenance of KRASmu cells; in fact, cancer cells utilize several metabolites derived from autophagic degradation of CAFs, resulting in resistance to different therapies including KRAS inhibitors." (PMID 37298264, 2023).
cancer (continued). "Altogether, this finding highlights that PDK4 and, possibly, all the PDK isoforms represent promising targets for cancer therapy of highly aggressive KRAS mutant cancers." (PMID 36835086, 2023). "On day 20 post THZ1 treatment, the relative proliferation rates of cancer cells T/Cs (%) were significantly lower in CAPAN2 (KRAS‐G12V) cells than in SW1990 (KRAS‐G12D) cells with both 5 mg/kg (50.0% vs." (PMID 38037549, 2023). "Given solid preclinical data, phase I dose escalation and expansion in KRAS G12C mutant cancers started in 2020." (PMID 37569406, 2023). "For many years, scientists have focused efforts on drugging KRAS and its effectors in hopes to provide much needed therapies for patients with KRAS-mutant driven cancers." (PMID 37108538, 2023). "Despite the limited efficacy of phase II trials in NSCLC patients, PLK1 is considered a synthetic lethal target in KRAS-mutant cancers, which are proved to be sensitive to mitotic perturbations and hypersensitive to the PLK1 suppression." (PMID 38104151, 2023). "In LUAD patients, almost all KRAS G12-mutant cancer patients were predicted to be KRAS dependent, albeit along a spectrum, and we found that the prediction scores were only correlated with some TCGA subtypes in the KRAS WT tumors." (PMID 37141389, 2023). "Studies have shown that in human malignant tumors, the incidence of RAS protein mutations is quite high, especially in ovarian cancer; the mutation status of KRAS codons 12, 13, and 61 ranges from 6 to 65% in different histo-types." (PMID 37298157, 2023). "Previous studies stated that the activation of KRas correlated with higher levels of expression of EGFR/MAPK in a plethora of human cancers." (PMID 37760426, 2023). "IB and IHC analysis confirmed target engagement, demonstrating that RASON inhibition sensitized KRAS mutant cancer cells to cetuximab through impairment of KRAS activation." (PMID 36241718, 2023). "The miR-143 high expression downregulates the downstream key molecules of the mTOR signaling pathway including HK2 and KRAS, thus influencing cancer cells metabolism reprogramming." (PMID 37208722, 2023). "In cigarette smoke–exposed mice, the correlation between let-7a expression level and the number of KRAS transversion at codons 12 and 13 was opposite between the cancer-free and cancer-bearing mice." (PMID 37511536, 2023). "KRAS mutant cancer cells can induce the transcription of SREBPs, promoting cholesterol synthesis and uptake." (PMID 36675307, 2023). "To highlight the importance of the cellular heterogeneity aspect of cancer coagulome we re-examined lung cancer single cell RNA seq data containing cells extracted from KRAS mutant tumors and corresponding normal lung tissues from each patient." (PMID 38188342, 2023). "Approaches to target KRAS-mutant cancers with inhibitors of MEK have failed, often due to the induction of RTK genes and/or their ligands." (PMID 37355626, 2023). "Chemotherapy was the initial recommended therapy for KRAS-mutant cancer patients, which was then replaced by or combined with immunotherapy." (PMID 36675641, 2023). "The finding of strong associations between cancer drivers, such as EGFR, KRAS and MET and their associated enhancers, further stresses the importance of epigenetic and genetic interaction during tumorigenesis." (PMID 37914932, 2023). "In patients with metastasis, those with KRAS G12C–positive cancer had a significantly higher prevalence of brain metastasis than patients with KRAS WT cancer (19.4% vs 13.2%; p = 0.002)." (PMID 37069542, 2023). "In contrast to KRAS, the presence of somatic mutations in the coding sequence of RRAS2 is very rare in human cancers." (PMID 38067115, 2023).
cancer (continued). "Herein, we evaluate the mutation profile of a 15-driver gene panel and copy number variation of KRAS in a large series of TGCT from a single reference cancer center." (PMID 37007070, 2023). "While mutant and hyperactive KRAS has been shown to induce and sustain cancer growth, other cellular programs can amplify these effects and provide alternative routes for cell survival upon KRAS inhibition." (PMID 37141389, 2023). "In other co-culture systems it was identified that cancer cell-derived PAI-1 mediated by KRAS can activate PSCs via IL-8 and aggravate the malignant action of cancer cells." (PMID 37409257, 2023). "We used INCERTS to discover antigen-specific TCRs from patients with cancer immunized with a novel mutant KRAS peptide vaccine." (PMID 37776855, 2023). "For example, KRAS is responsible for most RAS-driven cancers, and BRAF has the highest basal activity among RAF isoforms." (PMID 38150000, 2023). "An examination of CERES scores among KRAS, NRAS, and BRAFV600E mutant cancer cell lines indicated that KRAS and NRAS mutant cells had a heightened reliance on CRAF for proliferation, while BRAFV600E mutant cells primarily depended on BRAF for their growth." (PMID 38111008, 2023). "The activation of mutant KRAS under its own promoter in pancreatic progenitor cells using Cre recombinase under the pdx promoter results in PanIN-like lesions and eventually cancer." (PMID 36975534, 2023). "For example, the hotspot KRAS codon G12 is substituted for a variety of other amino acids within cancer samples." (PMID 37454202, 2023). "Research has indicated that KRAS-dependent cancer cells produce exosomes rich in survivin, promoting cancer cell survival and resistance and ultimately leading to poor prognosis." (PMID 37803304, 2023). "A previous study reported that the anaplerotic TCA cycle is an indispensable role of Gln in KRAS-mutant cancer, which is consistent with our work presented herein." (PMID 37937641, 2023). "Most PDACs harbor oncogenic KRAS mutations and elevated MYC signaling leading to dysregulation of global transcription and proliferation, potentially sensitizing cancer cells to therapeutic targeting with transcriptional inhibitors." (PMID 37831776, 2023). "In recent years G-quadruplex structure (G4) formation in the KRAS promoter was identified in cancer cells with effects on active oncogene expression, increased genomic instability, and telomere maintenance." (PMID 37268708, 2023). "Because KRAS and NRAS mutations also occur in many other cancers, there have been worldwide efforts to develop RAS inhibitors, including salirasib, which selectively disrupts the binding of the active RAS protein to the plasma membrane." (PMID 37079001, 2023). "MAPK-specific non-genomic RXR crosstalk has been demonstrated in HER2+ and KRAS-driven cancer models." (PMID 37686465, 2023). "The proto-oncogene KRAS is considered to be the most common gene driver of oncogenesis in human cancers." (PMID 37457560, 2023). "Concordant with elevated GM3 levels in KRAS mutant cell lines, high-level expression of ST3GAL5, which encodes GM3S, correlated with shortened survival time in KRAS mutant cancers." (PMID 36709325, 2023). "The regulation of oxidative stress in KRAS-driven cancers has been important in fully understanding KRAS-dependent cancer progression." (PMID 37649607, 2023). "circIFNGR2 was overexpressed in both wild type and mutant KRAS mutant cancer tissue compared with normal tissue." (PMID 36639711, 2023). "KRAS, one of the three RAS genes, for example, is a necessary protein to study due to its frequent mutations in certain cancers." (PMID 36769189, 2023). "FOXM1 is a spatiotemporally expressed master TF activated by aberrant KRAS signaling to drive cancer initiation, self-renewal, and proliferation." (PMID 37191407, 2023). "Concordantly, we found increased B4GALT5 transcripts in human KRAS mutant cancers and elevated LacCer levels in cells expressing KRASG12V." (PMID 36709325, 2023).
cancer (continued). "For example, it was reported that statin-mediated inhibition of RAS prenylation activates endoplasmic reticulum (ER) stress to enhance the immunogenicity of KRAS-mutant cancer." (PMID 37110848, 2023). "Among these, KRAS-driven cancers are characterized by upregulated glycolysis, glutaminolysis, and nucleotide biosynthesis." (PMID 37147673, 2023). "Median OS was numerically longer in patients with KRAS G12C vs KRAS WT cancer treated with 1L CIT (30.2 vs 10.6 months, respectively) or 2L CIT (11.3 vs 7.6 months, respectively)." (PMID 37069542, 2023). "Because KRas signaling triggers cell proliferation and survival, we measured the proliferation and concentration of cancer cells in tissues after treatment." (PMID 37813486, 2023). "Drug sensitivity testing revealed that a KRAS pathway inhibitor exerted strong anti‐cancer effects on the SCCC organoid compared to a MYC inhibitor, which were also confirmed in the xenograft model." (PMID 36691316, 2023). "KRAS-targeted drugs, such as sotorasib and adagrasib, are emerging for their anti-cancer activity in heavily pre-treated patients harboring the KRASG12C mutation." (PMID 37538108, 2023). "Research showed that KRAS-amplified cancers are insensitive to MAPK blockade due to adaptive response by rapidly increasing KRAS-GTP levels." (PMID 37808191, 2023). "Multiple KRAS mutant cancer cell lines, such as those from NSCLC, PDAC, CRPC, etc., were significantly inhibited from proliferation with this compound." (PMID 38001644, 2023). "Patients with aNSCLC with KRAS G12C mutations who were treated with 1L and 2L chemotherapy, and combination CIT and chemotherapy had similar OS compared with patients with KRAS WT cancer." (PMID 37069542, 2023). "CERS, ASAH, and ACER gene expressions, which each contributes ceramide synthesis and degradation, were used to compare the characteristics of wild-type KRAS and KRAS mutant cancers." (PMID 37758931, 2023). "A validation cohort of 39 cancer patients and 82 healthy controls was studied to validate KRAS detection rates in early-stage PDAC patients." (PMID 36900248, 2023). "Initially, we screened a chemical compound library for potential anticancer agents, and identified ARL-17477 with micromolar anticancer activity against a wide spectrum of cancers, preferentially affecting cancer stem-like cells and KRAS-mutant cancer cells." (PMID 37402770, 2023). "This strong and consistent enrichment of KRAS signaling likely reflects a bias towards cancer-related experiments in the DEET database." (PMID 36694664, 2023). "These two studies highlight possible alternative routes for KRAS-mutant cancer treatment beyond small molecule inhibitors." (PMID 37190303, 2023). "These cancers share a notable dependency on aberrant KRAS expression through activation of canonical ‘‘proximal’’ effectors, mainly the RAF-MEK-ERK and the PI3K-AKT-mTOR pathways." (PMID 37210549, 2023). "In cells with mutant KRAS, this led to suppressed downstream signalling and cancer cell growth, suggesting that common KRAS mutants found in cancer depend on nucleotide exchange for activation." (PMID 37258666, 2023). "More than 20% of several major cancer types, including pancreas, lung, and colon are driven by mutations in RAS genes, with KRAS comprising the bulk of those mutations." (PMID 37604828, 2023). "RAS genes (HRAS, KRAS, and NRAS) comprise the most frequently mutated oncogene family in human cancer, accounting for 3.5 million new cases yearly, worldwide." (PMID 36858798, 2023).
cancer (continued). "KRAS, one of the three RAS isoforms (KRAS, HRAS, NRAS), is the most frequently mutated RAS protein in cancer patients, and G12, G13, and Q61 are three hot spots among the oncogenic mutations." (PMID 37268708, 2023). "Although KRAS mutations or fatty acids have been correlated with ROS production to modulate cancer progression, the role of ROS in KRAS- and fatty acid-driven CRC cells has remained elusive." (PMID 37649607, 2023). "The dependence on both autophagy and UPS by KRAS-mutant cancer cells makes proteostasis dysregulation a convincing therapeutic approach." (PMID 36923647, 2023). "Although it was not statistically significant, a difference in the family history of cancer was observed, with 2.9% of the KRAS wild-type patients having at least one case of cancer in the family compared with 5.7% in the KRAS-mutant group." (PMID 37761297, 2023). "On top of that, CCK8 assay result showed that the higher concentrations of KRAS led to lower anti-cancer effect of cetuximab." (PMID 36639711, 2023). "mSTK11-mKEAP1 was more prevalent in patients with KRAS G12C–positive cancer vs KRAS WT cancer (14.3% vs 9.9%; p = 0.012)." (PMID 37069542, 2023). "Concordantly elevated expression of these same biosynthetic pathways is observed in KRAS mutant cancers and correlate with poor clinical outcomes." (PMID 36709325, 2023). "A recent study reported the efficacy of CDK4/6–SHP2 co-inhibition in KRAS-mut cancers, which is consistent with our KRAS-amp GEA results." (PMID 36752207, 2023). "Dysregulation of KRAS leads to various hallmarks of cancer like proliferation, metabolic reprogramming, anti‐apoptosis, and metastasis." (PMID 36708238, 2023). "With an efficient intracellular antibody delivery system, this can be further developed as combinatorial therapeutics for CRC and other KRAS-driven cancers." (PMID 37051535, 2023). "KRAS mutation causes elevated secretion of VEGF and CXCL1, which support cancer progression and development." (PMID 36986550, 2023). "Recently, two cetuximab-decorated gelatin-based KRASG12C-specific siRNA delivery systems showing successful KRAS oncogene knockdown leading to sensitization of the cancer cells to gefitinib were described in the literature." (PMID 36865093, 2023). "KRAS mutations in NSCLC usually signify a poor prognosis and are linked with resistance to multiple cancer treatments." (PMID 36702816, 2023). "The presence of a KRAS mutation and overexpression of GLUT1 worsened the survival rate of cancer patients." (PMID 37110218, 2023). "One Crohn-related non-SRC-type SB-PCC harbored a frameshift deletion of the CTNN1A gene, along with KRAS and MYC amplifications, while a CDH1 mutation was identified in another cancer (SRC type, Crohn related)." (PMID 36812376, 2023). "At 1L initiation, patients with KRAS G12C–positive cancer had a significantly higher prevalence of metastasis than patients with KRAS WT cancer (85.9% vs 78.5%; p = 0.001)." (PMID 37069542, 2023). "In the mechanism exploration, RNA pull-down experiments and dual-luciferase experiments helped us to determine that hsa_circ_0001846 regulated the KRAS expression by sponging miR-204-3p in PC, thus playing a pro-cancer role." (PMID 38081815, 2023). "Here we report the discovery of a novel protein, termed RAS-ON (RASON), that plays a critical role in oncogenic RAS signaling and represents a vulnerable therapeutic target for mutant KRAS-driven cancers." (PMID 36241718, 2023). "This real-world study showed that patients with KRAS G12C–positive or KRAS WT cancer have similar OS in the 1L or 2L when treated with chemotherapy or combination CIT and chemotherapy." (PMID 37069542, 2023). "The apoptosis‐inducing effect of THZ1 was markedly stronger in KRAS‐G12V PDAC than KRAS‐G12D cancer." (PMID 38037549, 2023). "KRAS is a component of epidermal growth factor receptors (EGFR) signaling that are vital molecules in cancer therapy." (PMID 37371705, 2023).